DSC2 (desmocollin 2)
Diseases named in the same sentence as DSC2 in open-access papers (continued):
Sharing a sentence is not in itself a finding about the gene and the disease.
viral infection (1 paper, 2025). "The median expression of some genes (CTBP1, LAPTM4B, CFAP45, DSC2, LAMP1, EXOG, RPS21, and SIRPB1) was higher in bacterial compared to viral infection." (PMID 41496780, 2025).
tumor (28 papers, 2006 to 2025). "Further studies are needed to clarify the association between desmocollin-2 expression and tumor cell apoptosis." (PMID 35054231, 2021). "DSC2 depletion is highly associated with poor tumor differentiation, regional lymph node metastasis and poor prognosis." (PMID 25119898, 2014). "The depletion of DSC2 is highly associated with poor tumor differentiation, regional lymph node metastasis and a poor prognosis." (PMID 25119898, 2014). "The loss of DSC2 initiates tumor cell metastasis by activating the β-catenin pathway and eventually inducing an epithelial-mesenchymal transition-like process." (PMID 25119898, 2014). "De novo expression of Dsc1 and Dsc3 was not entirely dependent on loss of Dsc2 as Dsc1 was expressed in all tumour specimens and Dsc3 was detected in three of eight samples that showed normal levels of Dsc2." (PMID 17088906, 2006). "However, specifically concerning tumor promotion, loss of DSC2 expression has only been reported to affect cell proliferation, invasion, tumor differentiation, and even metastasis in ESCC, one of the EC subtypes." (PMID 40872572, 2025). "However, other studies have shown that the downregulation of the adhesion junction component E-cadherin and the desmosome components DSG2 and DSC2 is associated with increased tumor metastasis and poor prognosis." (PMID 41381723, 2025). "Loss of DSC2 can activate Akt signaling pathway and promote tumor proliferation." (PMID 36367775, 2022). "Additionally, a significant association between DSC2 expression in the primary tumour and an increased frequency of cerebral and lung metastasis could be observed." (PMID 36927383, 2023). "Consistent with the findings of previous studies, this analysis confirmed the specific expression of DSC2 in TNBC tumor cells." (PMID 38539508, 2024). "This suggests that the increased attachment rate of DSG2 expressing tumor cells is independent from the hepatic expression of the classical binding partners Dsg2 or Dsc2." (PMID 39107343, 2024). "The extremely high reduction in CLU and DSC2 levels found in our microarray study following HLA-G expression is consistent with HLA-G-favoring tumor progression." (PMID 39358558, 2024). "In vivo DSC2 knock down reduces the amount of circulating tumour cells and clusters, and consequently the amount and size of established brain metastases and established metastatic lesions in lung tissue." (PMID 36927383, 2023). "Here, we identified that DSC2 functioned as a pivotal tumor suppressor in GC by inhibiting the nuclear translocation of γ-catenin and inactivating the PTEN/PI3K/AKT signaling pathway." (PMID 37421607, 2023). "Reduced DSC2 tumour expression decreases the amount of viable tumour cells in the blood circulation—CTCs as well as CTC clusters—and, as a consequence, reduces the effective formation of distant metastases." (PMID 36927383, 2023). "In this work, we constructed GC cells with both the downregulation and upregulation of DSC2, established mouse tumor xenograft models, and evaluated the effect of DSC2 on GC cell viability in vitro and in vivo." (PMID 37421607, 2023). "The tumor weights in the sgRNA-NC group, sgRNA-DSC2 group, lenti-NC group, and Lenti-DSC2 group were (2.43 ± 0.33) g, (4.29 ± 0.38) g, (2.45 ± 0.73) g, and (0.70 ± 0.19) g, respectively." (PMID 37421607, 2023). "In an in vivo brain dissemination xenograft mouse model, reduced expression of DSC2 in the brain-seeking TNBC cells led to a decreased amount of circulating tumour cells/clusters and, in turn, to fewer and smaller brain metastatic lesions." (PMID 36927383, 2023). "No significant trend was observed between the patients’ overall survival and the level of DSC2 expressed in their tumour." (PMID 36927383, 2023). "Firstly, in order to compare the expression level of DSC2 between normal osteoblasts cells (OB cells) and tumor cells, we conducted single cell RNA seq analysis." (PMID 37779876, 2023).
tumor (continued). "Functionally, DSC2 promotes tumour cell aggregation and, in turn, fosters the formation of tight CTC clusters with high metastatic potential." (PMID 36927383, 2023). "While all positive stained luminal samples showed a moderate staining (2 < IRS < 6), approx. 20% of HER2 positive and TNBC tumours displayed a strong DSC2 staining (IRS > 6)." (PMID 36927383, 2023). "On the contrary, the overexpression of DSC2 dampens tumor growth in vivo whereby xenograft tumor sizes in the Lenti-DSC2 group were significantly smaller than those in the lenti-NC group." (PMID 37421607, 2023). "Previous studies from our laboratory have identified four genes (ANP32E, DSC2, ANKRD30A and IL6ST/gp130) that are specific to TNBC and were associated with lymph node metastasis (LNmets), the earliest indicator of tumor progression via distal spread." (PMID 35387118, 2022). "With respect to tumorigenesis, DSC2 has been demonstrated to be involved in the development of several types of tumor." (PMID 25119898, 2014). "In comparison, the present study demonstrated that DSC2 suppresses tumor cell-cell adhesion by opposing the localization of adherens junction molecules and keratin intermediate filament retraction and F-actin cytoskeleton rearrangement." (PMID 25119898, 2014). "In TβRII KO tumor epithelium compared with TβRIIfl/fl epithelium, Igfbp4 and Tspan13 expression was upregulated while Col1α2, Bmp7, Gng11, Vcan, Tmeff1, and Dsc2 expression was downregulated." (PMID 22748014, 2012). "In tumour samples, Dsc2 showed both a reduction in expression and a relocalisation from the membrane to the cell cytoplasm." (PMID 17088906, 2006). "Furthermore, cell–cell interaction analysis revealed that the DSC2 gene interacts with the DSG2 gene within tumor cells, and pathway analysis verified the upregulation of the DSC2–DSG2 protein complex structure specifically in TNBC." (PMID 38539508, 2024). "Furthermore, tumor cells with high DSC2 expression exhibit increased metastatic potential, tumor cell cohesion, and resistance to chemotherapy." (PMID 38539508, 2024). "DSC2 expression was observed exclusively in tumour cells in all biopsies." (PMID 36927383, 2023). "In positively stained tumour cells, we observed mainly a membranous staining, although DSC2 could be also detected in a minority of samples within the cytosol." (PMID 36927383, 2023). "DSC2 may serve as an oncogene, which exert a crucial role in tumor progression, predicting prognosis and immune cell infiltration in OS." (PMID 37779876, 2023). "Desmocollin-2 (DSC2) mediates intercellular adhesion and is involved in tumour progression." (PMID 37779876, 2023). "Furthermore, overexpression of DSC2 was found to promote tumor cell clustering, thereby improving cancer cells survival and metastasis." (PMID 37779876, 2023). "Indeed, a possible explanation for the contrary findings is that enhanced tumour cell aggregation through DSC2 up-regulation is a factor which favours the development of CTC clusters, which have a considerably higher metastatic potency than singular CTC." (PMID 36927383, 2023). "Interestingly, higher DSC2 expressing aggregates showed lower apoptotic rates than the corresponding control clusters when treated with cisplatin and, correspondingly, reduced DSC2 expression significantly enhanced tumour cell response to cisplatin." (PMID 36927383, 2023). "The volume and weight of the tumors from the mice injected with DSC2-overexpressing LM3 cells were significantly lower than those from the mice injected with the vector-transfected cells (P < 0.001 for both), indicating that DSC2 overexpression inhibited the tumor growth dramatically." (PMID 36367775, 2022). "The study showed that DSG2 and DSC2 play opposite roles in tumor proliferation." (PMID 33407183, 2021). "We thus suggest that inhibition of desmocollin-2 expression in tumor tissue may impede the activation of cell apoptosis." (PMID 35054231, 2021).
tumor (continued). "This association was further substantiated by the findings that tumours lacking PR- and ER- expression were likewise individually significantly associated with high DSC2 levels (all bands: p = 0.046 and p = 0.04 and upper band: p = 0.054 and p = 0.012 respectively)." (PMID 36927383, 2023). "Dsc2 expression was lost in all 16 colitic tumours that showed loss of E-cadherin (data not shown)." (PMID 17088906, 2006). "Another notable interaction was the interaction between DSC2 and DSG2 in tumor cells, where the former is one of the 12 TNBC markers we identified." (PMID 38539508, 2024). "Another key finding of our study was the interaction between the DSC2 and DSG2 genes among TNBC tumor cells, suggesting that they are more tightly aggregated with each other than those of other subtypes, including normal epithelial cells." (PMID 38539508, 2024). "In vitro, ectopic DSC2 expression or DSC2 down-regulation in MDA-MB-231 and MDA-MB-231-BR led to a significant tumour cell aggregation increase and decrease, respectively." (PMID 36927383, 2023). "Results indicated that the formation of tumor cell colonies was significantly inhibited in overExp-DSC2-transfected LM3 cells (P < 0.01), while promoted in shRNA-DSC2-transfected 7721 cells (P < 0.05)." (PMID 36367775, 2022). "Remarkably, we have also found that the expression of PD-L1, which has an immunosupressive function in the anti-tumor immune reaction, correlated inversely with EMT transcription factors related to barriers (CDH2, CAV2, DSC2, and IL1RN)." (PMID 34527572, 2021). "Desmocollin-2 (DSC2) and DSG2, two transmembrane cell adhesion proteins of desmosomes, were reported with opposite functions in tumor progression." (PMID 27107420, 2016). "Specifically, lower expression of APC, DCC, and DSC2 and higher expression of MACC1 was observed in the tumor samples relative to the paired adjacent normal tissue in both the microarray and qPCR assays." (PMID 22363440, 2012). "In addition, reduced expression of desmocollin 2 (DSC2), a calcium-dependent cell–cell adhesion transmembrane glycoprotein, favors tumor progression and poor survival through redistributing adherent junctions." (PMID 39358558, 2024). "Specifically, twelve marker genes, including DSC2 and CDKN2A, were identified for TNBC tumor cells." (PMID 38539508, 2024). "Furthermore, other members of the desmosomal cadherin family were expressed at low level in a small number of TCGA tumors, and DSG1, DSC2 and DSC3 were all significantly enriched in the DSG2-high tumor subset." (PMID 27340778, 2016). "This in turn affected cytoskeleton arrangement, possibly through alternative signaling pathways, which ultimately led to uncontrolled migration of tumor cells lacking DSC2." (PMID 25119898, 2014). "Desmocollin-2 (DSC2), a transmembrane glycoprotein belonging to the desmosomal cadherin family, has been found to be differentially expressed in several types of cancer and to be involved in tumor progression." (PMID 25119898, 2014). "We identified several components of desmosomes – Dsp, Dsg2, desmocollin 2 (Dsc2; MGI: 103221), and plakophilin 2 (Pkp2; MGI: 1914701) – whose expression was significantly downregulated in the highly invasive tumor lesions that develop in the RT2 mouse model of PNET." (PMID 20862307, 2010). "Also, primary tumours from patients that developed brain metastases showed higher DSC2 levels than those with no cerebral metastases (p = 0.012)." (PMID 36927383, 2023). "Interestingly, neither the suppression nor overexpression of DSC2 regulated the total levels of γ-catenin in either of the GC cells or mouse tumor xenografts." (PMID 37421607, 2023). "Transcription of Dsc2 was not altered in any of the four tumours." (PMID 17088906, 2006).
tumor (continued). "Thus, although an increase in Dsc2 message levels was found in one sample, the majority (six of seven) showed no significant changes in Dsc2 transcription (i.e. there was <2-fold difference in expression levels between tumour samples and matched controls)." (PMID 17088906, 2006). "We found one unique salivary exosome protein, desmocollin-2, present in the PreD group that was absent in the DMBA-induced tumor tissue, as reported in other studies." (PMID 35054231, 2021). "In contrast, we did not observe any effect of DSC2 up- or down-regulation on the chemosensitivity of both TNBC cell lines cultured as a monolayer, indicating that the DSC2-mediated cohesiveness of the 3D tumour cell clusters is the main reason for the altered chemosensivity." (PMID 36927383, 2023).
cancer (26 papers, 1990 to 2025). A tumor composed of atypical neoplastic, often pleomorphic cells that invade other tissues. "Recent evidence has demonstrated that Mutations and abnormal expression of DSC2 often lead to dysfunction of desmosome, which further cause the metastasis and progression of cancer cell in some malignant solid tumor." (PMID 37779876, 2023). "It is not surprising to find associations between longer genes and cancer and heart pathologies often caused by mutations in particularly long genes, like DSC2 and TTN." (PMID 33643374, 2021). "In addition, Dsg2 and Dsc2 mRNA levels were both negatively associated with individual cancer stages and nodal metastasis status of BC in TCGA database." (PMID 38671389, 2024). "Considering Dsg2 and Dsc2 affected EGFR signaling pathway in some cancers such as cancers of gallbladder, colon, cervix and the lungs, we focused on EGFR phosphorylation and its major downstream AKT and ERK pathways." (PMID 38671389, 2024). "Aberrant expressions of desmoglein 2 (Dsg2) and desmocollin 2(Dsc2), the two most widely distributed desmosomal cadherins, have been found to play various roles in cancer in a context-dependent manner." (PMID 38671389, 2024). "It was reported that deregulation of Dsg2 and its partner Dsc2 contributed to initiation and progression of cancers in a context-dependent manner." (PMID 38671389, 2024). "As mentioned, desmosomal proteins and specifically DSC2 have been previously investigated in the context of cancer research." (PMID 36927383, 2023). "Several studies have found that DSC2 proteins are abnormally expressed in various types of cancer and correlate with cell proliferation and invasive behaviour, and showed that a high expression of DSC2 increased cell aggregation." (PMID 36927383, 2023). "Down-regulation of DSC2 mediated by miR-25 promotes the proliferation and invasiveness of cancer cells by redistributing β-catenin and activating the β-catenin signaling pathway." (PMID 36367775, 2022). "Recently, studies have found that the expression of DSC2 is abnormal in many human cancers, and it is related to the prognosis of tumors." (PMID 36367775, 2022). "Most GCs are positive for DSC2, and this gene is frequently upregulated in cancers with intestinal phenotype." (PMID 32560392, 2020). "For example, a module containing gene DSG2, PKP2 and DSC2, is served as both inflammation and cancer module." (PMID 26489668, 2015). "Several studies have found that DSC2 proteins are abnormally expressed in various types of cancer and correlate with cell proliferation and invasive behavior." (PMID 25119898, 2014). "However, little is known about roles of Dsg2 and Dsc2 on tumorigenesis and progression in BC, which is the most common cancer among women." (PMID 38671389, 2024). "Our finding suggests that DSC2 might be a potential therapeutic target for the treatment of cancers, most especially GC." (PMID 37421607, 2023). "A study on CRC cells shows Dsc2 is switched to Dsc1 and Dsc3 during cancer development." (PMID 35194111, 2022). "A reduction in Dsc2 protein expression was found in eight of 16 sporadic cancer specimens examined." (PMID 17088906, 2006). "Besides, DSC2 was differentially expressed in TNM stage of different cancers." (PMID 37779876, 2023). "In addition, the reduced expression of DSC2 was reported in different types of cancer." (PMID 35159392, 2022). "Desmocollin 2 and 3 (DSC2 and DSC3) expressions are well-known prognostic indicators in various cancers, related to adhesive strength, cytoskeletal arrangement, and cell adhesion." (PMID 40872572, 2025). "In contrast, ginsenoside Rg1 downregulated the mRNA expression of ARG2, MMP1, S100A4, and RAPSN, and upregulated the mRNA expression of LAMC2, DSC2, KRT6A, and FOSB, thereby enhancing the anti-cancer function of granulocytes inhibited by NA." (PMID 36817446, 2023).
cancer (continued). "This heatmap, based on a dataset including samples from NILM, ASC-US, and ≥LSIL groups, displays two main clusters: cancer markers (MCM3, CEACAM5, S100P, ICAM1) on the left and healthy markers (CRNN, EVPL, DSC2) on the right side of the figure." (PMID 37445651, 2023). "Other possible biomarkers that hold immense potential in GC include actin-related protein 2/3 (APR 2/3), desmocollin 2 (DSC2), B7H6 ligand, neuropilin-1 (NPR-1), cancer-related antigens CA-72-4 and CA-19-9, and anion exchanger 1 (AF1)." (PMID 35814023, 2022). "Key among these novel biomarkers are the B7H6 ligand, actin-related protein 2/3 (ARP 2/3), neuropilin-1 (NRP-1), desmocollin 2 (DSC2), anion exchanger 1 (AF1), and cancer-related antigens CA-72-4 and CA-19-9." (PMID 32560392, 2020). "Some are supported as important in linking inflammation and cancer, for example PKP2, DSG2 and DSC2." (PMID 26489668, 2015). "Our previous study demonstrated that the expression of DSC2 in ESCC gradually decreases between regions exhibiting esophageal hyperplasia to regions of dysplasia and carcinoma in situ." (PMID 25119898, 2014). "Previous studies have verified that several desmosomal proteins are dysregulated in diverse human cancers, but the role of DSC2 in HCC has not been investigated so far." (PMID 36367775, 2022). "We found four paired lncRNA-mRNA exhibiting a substantially high SCNA frequency in cancers, including lncRNA FGD5-AS1 and PRKAR2A (KIRC, 44.2% and 44.4%), lncRNA TUG1 and CDC7 (LUAD, 25.9% and 23.6%), lncRNA TUG1 and DSC2 (LUAD, 25.9% and 26.1%) and lncRNA SNHG7 and PNMA2 (LUAD, 25.4% and 31.1%)." (PMID 32846981, 2020).
cardiovascular disease (5 papers, 2015 to 2025). "We screened 404 genes related to inherited cardiovascular disease and confirmed that no deleterious mutations were present in other desmosomal genes, including DSC2, DSG2, JUP, and DSP, involved in the etiology of AC." (PMID 35063130, 2022).
infection (5 papers, 2010 to 2026). The state of being infected such as from the introduction of a foreign agent such as serum, vaccine, antigenic substance or organism. "The infection also significantly downregulated the expression of dsc2 when compared to the controls and the expression of muc5b when compared to challenged vaccinated fish." (PMID 35173716, 2022). "The infection process of EBV relies on interactions between the virus and specific receptors on the surface of host cells, including CD21, NRP1, EphA2, and, more recently, discovered receptors such as R9AP and DSC2." (PMID 42112902, 2026). "By contrast, P. gingivalis did not degrade CDH1, DSC2, or NECTIN1 at 1 h after infection." (PMID 31697789, 2019).